MIR4311 (microRNA 4311)
Synonyms: hsa-mir-4311
Gene: MicroRNA gene on chromosome 15 (66,040,233 to 66,040,332, forward strand). Ensembl gene ENSG00000263512.
Diseases named in the same sentence as MIR4311 in open-access papers:
MIR4311 is named in the same sentence as 1 disease in open-access papers, as found by Europe PMC text mining. Sharing a sentence is not in itself a finding about the gene and the disease. The quoted sentences say what the papers report.
breast carcinoma (1 paper, 2020). "Three genes (CLCA2, SPIC, MIR4311) were associated with overall and breast cancer specific survival in this discovery cohort." (PMID 32298355, 2020).